CD4 (CD4 molecule)
Diseases named in the same sentence as CD4 in open-access papers (continued):
Sharing a sentence is not in itself a finding about the gene and the disease.
influenza (continued). "Examination of CCR6 expression on vaccine-primed Th17 cells demonstrated a heterogenous profile 5 days after influenza challenge with approximately 50% IL-17A+ CD4+ T cells lacking the chemokine receptor." (PMID 24465206, 2014). "Vaccination also did not appear to affect the frequency of influenza-specific CD4+ or CD8+ T cells expressing Granzyme B and at least IFN-γ, and/or IL-2." (PMID 25078387, 2014). "Following influenza vaccination, peripheral blood mononuclear cells (PBMCs) were obtained and analysed by flow cytometry for T-regs, CD4+ and CD8+ T-cell subsets (CCR7+CD45RA+, CCR7-CD45RA+ and CD28-CD57+) and CMV-reactive CD4+ and CD8+ T-cells." (PMID 25275464, 2014). "In contrast, the influenza infection in non-vaccinated control mice predominantly drove the induction of IFNγ-producing CD4+ T cells." (PMID 24465206, 2014). "Recent studies have suggested the source of IL-10 in the context of an influenza infection may be CD4+ and CD8+ T cells, and IL-10 expression is a high correlate to survival/protection against influenza." (PMID 24719769, 2014). "In mice receiving vectors expressing HA stem alone or HA stem/M2e fusion protein, levels of influenza-specific CD4+ T cells were not significantly higher than those in mice receiving wtMVA or PBS control." (PMID 24523886, 2014). "Additionally, whole virus influenza vaccines have been found to stimulate protective immunity in murine challenge models by inducing influenza-specific CD8+ CTL and CD4+ Th cells as well as neutralizing antibodies." (PMID 25072749, 2014). "While there is a general increase in memory CD4 T cells at the expense of naïve CD4 T cells in aged subjects, the number of circulating influenza-specific CD4 T cells does not seem to differ." (PMID 24155927, 2013). "The impact of yearly influenza vaccination or repetitive influenza virus infections on memory CD4 T cell responses is not well defined." (PMID 24155927, 2013). "The IL-2+ producing T cell bias was not due to overlap of the IL-2+ T cells with T follicular helper (Tfh) cells, as the majority of both IFNγ+TNFα+ and IFNγ−IL-2+TNFα+ influenza-specific cells responding to CA/09 and NC/99 were found within the CXCR5− CD4 T cell population." (PMID 23526940, 2013). "Antigen processing via the major histocompatibility complex (MHC) Classes I and II pathways and subsequent induction of a CD4+ and, to a lesser extent, CD8+ T cell (CTL) responses are also observed following vaccination with seasonal inactivated influenza vaccines." (PMID 24066003, 2013). "Influenza infection stimulates protective host immune responses but paradoxically enhances lung indoleamine 2,3 dioxygenase (IDO) activity, an enzyme that suppresses helper/effector T cells and activates Foxp3-lineage regulatory CD4 T cells (Tregs)." (PMID 23785507, 2013). "Studies have shown that influenza-specific memory CD4+ T cells can directly protect against influenza infection in the absence of B cells or CD8+ T cells." (PMID 24204639, 2013). "This might be of particular interest, since it was shown that CD4+ and CD8+ T-cell responses to influenza could partially confer protection from heterologous IAV infection." (PMID 23967287, 2013). "A clear majority among all epitope-specific CD4 T cells in the MedLN and spleen of B10 mice after NC infection secreted IFN-γ, consistent with previous studies and the generally accepted Th1 nature of the response to influenza infection." (PMID 22457834, 2012). "This outcome is similar to observations of influenza infection in which IL-1R and NLRP3-inflammasome deficient animals display defective CD4+ and CD8+ T lymphocyte responses in the absence of increased inflammation." (PMID 23209411, 2012). "Given the potential impact of infection with influenza, the minor and transient effect on CD4+ T cell numbers from the vaccine itself should probably not be a consideration for HIV-infected individuals." (PMID 22937824, 2012).
influenza (continued). "We have previously shown that HIV-infected adults had no depreciation in peripheral blood influenza-specific cytokine-secreting effector memory CD4+ T-cells." (PMID 22715399, 2012). "For instance, in models of influenza infection, CD11b−CD103+ DCs participate in the induction of CD4+ and CD8+ T cell responses, whereas CD11b+ DCs seem unable to activate naïve T cells, and could rather participate in the recruitment of effector cells." (PMID 23300898, 2012). "Although the CD4-driven cellular immune response plays an important role in the defense against influenza, it is concluded that it does not contribute to the clade-specific differences in protection." (PMID 21283631, 2011). "Moreover, we demonstrated that GSI-mediated inhibition of Notch signaling attenuated overall IFN-γ production and resulted in fewer numbers of IFN-γ+CD4+ and IFN-γ+CD8+ T cells in our influenza model." (PMID 22072963, 2011). "For example, using a mouse model of influenza infection, it was shown that primed transgenic CD4+ T cells that were specific for ovalbumin (with no cross-reactivity to flu) migrated efficiently to the infected lung." (PMID 22216008, 2011). "Moreover, in a randomized, double-blind comparative trial of subunit and virosomal influenza vaccines for immunocompromised patients, suppression of VL with HAART was a more important predictor of response to influenza vaccination than the CD4 count." (PMID 22194853, 2011). "Although mice lacking both CD8 and B cells died after influenza infections, mice lacking CD4 and B cells survived." (PMID 20667098, 2010). "The role of both CD4+ T-cell and CD8+ T-cell in influenza infection have been extensively studied." (PMID 20174650, 2010). "Thus, CD8 T cells do not play a significant role in the enhanced protection against influenza infection in the PCN-treated mice, whereas, both B cells and CD4 T cells are critical for full protection." (PMID 19774076, 2009). "In contrast to the lack of induction of CD4 responses, IKDCs presented influenza derived OVA epitopes to CD8+ T cells (53% recuited into cell division), however to a degree similar to B220−NK cells (62% recuited into cell division)." (PMID 19784375, 2009). "Although antibodies appear to facilitate the recovery from influenza infection, it is generally believed that B cells cannot produce neutralizing, isotype-switched, influenza-specific antibodies in the absence of CD4 T-cell help." (PMID 18258091, 2008). "Influenza alone mice had slightly more CD4+ CD44+ and CD8+ CD44+ cells than no treatment mice in BALF, especially with smoke exposure." (PMID 18627612, 2008). "Our findings do however support the premise that the major target of IL-6 activity in our influenza model is the Treg population rather than conventional CD4+ T cells." (PMID 18389078, 2008). "We found that the activity of a subset of influenza-specific memory T cells (CD4+ T cells) was diminished in the absence of IL-6 due to the inhibitory effects of regulatory T cells—an effect that compromised protective anti-viral immunity." (PMID 18389078, 2008). "In studying the pNP-induced correlates of immunity to H1N1 influenza in the mouse, we have shown here that these synthetic consensus vaccines are able to induce both CD4+ and CD8+ cellular immune responses capable of providing protection from influenza infection." (PMID 18575608, 2008). "Our analysis also identified baseline levels of fluA-specific IFN-γ+ CD4 T-cells as a significant baseline correlate for both CD4 and CD8 T-cell responses to influenza vaccination with an inverse correlation, even though the association is only modest in strength." (PMID 18596908, 2008). "In HIV-infected persons, influenza vaccines may result in an increase in HIV plasma level and/or a reduction in CD4 cell counts." (PMID 16965629, 2006).
influenza (continued). "For instance, in influenza, the CD8+ restricted epitopes have all been largely identified for some time, particularly in the BL/6 model system; in contrast, only very recently have confirmed CD4 epitopes been found, and they are much more poorly characterized." (PMID 16494717, 2006). "Importantly, aged unvaccinated D + Q treated mice had impaired viral clearance at 15 DPI, suggesting that improvements in CD4 T cell differentiation did not have positive effects on overall flu outcomes." (PMID 41462563, 2026). "Anatomical, temporal and genomic coordination of cellular and molecular events dominated by CD4+ Tfh in the draining, but not the non-draining, lymph node is characteristic of an optimal immune response to adjuvanted seasonal influenza vaccine in young adults with African or Asian ancestry." (PMID 41317665, 2025). "Recent studies employing ultrasound (US)-guided FNA to sample draining LNs (dLNs) have utilised FNA-derived dLN cell profiling to demonstrate the evolution of B and CD4+ Tfh cell responses to non-adjuvanted influenza and COVID-19 mRNA vaccination weeks and even months after immunisation." (PMID 41317665, 2025). "A second dose may be needed to optimize CD4 T cell‐mediated immunity, which may offer a broader and longer lasting protection against symptomatic influenza, even in the absence of neutralizing antibodies." (PMID 40045876, 2025). "While the antibody response to influenza vaccines has been the main focus of protection, a cell-mediated immune (CMI) response, in particular CD4+ and CD8+ T-cells, towards the well-conserved internal influenza nucleoprotein (NP) could be an alternative and complementary path for protection." (PMID 40573889, 2025). "In addition, previous work with patients infected with SARS-CoV-2 or influenza has demonstrated increased proportions of CD8+ Treg cells during these infections but no change in CD4+ Treg cells." (PMID 39806065, 2025). "Inducible deletion of Hif1a in CD4 T cells, at the onset of its activity in the lung but after initial T‐cell priming in SLO, led to reduced numbers of Th1 cells, alveolar macrophages, and lung‐resident NK cells, as well as diminished influenza‐specific IgA titers." (PMID 40815083, 2025). "Current vaccine strategies, including seasonal influenza vaccines, are not specifically designed to engage CD4+ T cells, despite their necessity in germinal center formation and long-lived humoral immunity, as well as their contribution to cellular immunity in infected tissues." (PMID 39283916, 2024). "While heterologous infection or immunization priming of CD4+ T cells was able to enhance the early GC cellular response following influenza challenge, we did not see corresponding increases in generating long-term HA-specific antibodies or antibody-secreting cells." (PMID 39283916, 2024). "However, despite the early enhancement of the germinal center cellular response after influenza challenge, heterologous infection or immunization priming of CD4+ T cells did not enhance HA-specific antibody titers." (PMID 39283916, 2024). "We next assessed whether the phenotype of the citrulline-specific CD4+T cells differed between the progressor and non-progressor individuals also in comparison to influenza-specific cells and the global CD4+T cell compartment." (PMID 39557489, 2024). "Overall, our findings suggest that heterologous infection or immunization priming of CD4+ T cells can be used to enhance both the early GC response, including the GC Tfh and GC B cell magnitude, and establishment of CD4+ TRM cells that respond to influenza challenge." (PMID 39283916, 2024). "Indeed, AdC68-HATRBD but not QIV vaccine, elicited robust SARS-CoV-2- and influenza-specific Th1-biased CD4+ and CD8+ T cells." (PMID 38509167, 2024). "Phenotypes could not be assessed for non-LC CD4+ T cell specificities or influenza-specific CD8+ T cell specificities at acute timepoints given the low tetramer counts." (PMID 39284068, 2024).
influenza (continued). "In several studies, it has been demonstrated that the induction of robust CD4+ T cell memory responses is important to provide help to B-lymphocytes, whereby conserved MHC Class II-restricted epitopes within HA are essential for B cells to respond to drifting influenza." (PMID 36986773, 2023). "In addition, TGFβ also controls the function of CD4+ and CD8+ T cells during influenza infection, which could also explain the marginal CD8+ responses obtained after immunization of mice with rNP plus BPPcysMPEG." (PMID 36986773, 2023). "When the persistence of CD4 and CD8 T cell reactivity in humans was tested, cross-reactivity was also found, which was likely due to the exceptionally broad epitope coverage and sequence conservation, even for receptor binding proteins such as influenza HA or SARS-Co-V-2 spike proteins." (PMID 36851752, 2023). "However, a study carefully linking CD4 T cells of defined specificity with the timing of appearance and magnitude of antigen-specific B cells and Abs upon influenza infection is still lacking." (PMID 37711622, 2023). "However, it is important to acknowledge that the adoptive transfer analyses in our study did not reveal a CD4+ T cell-intrinsic defect in TFH cell differentiation in the absence of Aiolos during influenza infection." (PMID 36964178, 2023). "Similarly, immunodominant CD4 T cell epitopes (401–430aa) largely overlap with neutralizing B cell regions in the influenza HA stem (PDB 5JVR), with 50% essential amino acids for MEDI8852 binding to the HA stem located within the highly immunogenic CD4 T regions (401–430aa)." (PMID 36016115, 2022). "Often, a defective cellular immunity leads to decreased memory B cell expansion and impaired antibody production, as occurs with H1N1/09 influenza vaccine non-responders where failure in CD4+ T cell stimulation and IL-2 secretion concurs with a low percentage of IgG antibody-secreting cells." (PMID 35860236, 2022). "Strikingly, however, viral Ag dependent proliferation and differentiation of naïve CD4+ T cells into effector Tfh cells took place normally and coincided with the appearance of hyperactive cDC2 subsets which accumulated in ICAM-1/2-/- MedLNs of influenza-infected mice." (PMID 36895258, 2022). "To assess memory CD4 T cell responses following SARS-CoV-2 infection, we screened 27 ADAPT subjects from the first wave (May-October, 2020) at 3 months post-infection using recombinant SARS-CoV-2 RBD protein, and using influenza lysate as a control antigen." (PMID 36544780, 2022). "Therefore, the pre-existing CD4 and CD8 T cell response may be measured about a half year earlier than the start of some epidemics, although those periods had minimal influenza activity based on surveillance data." (PMID 35858844, 2022). "However, the cellular immune response to influenza vaccination was not affected by rituximab, with similar levels of influenza-specific CD4+ cells in patients treated with rituximab or DMARDs." (PMID 35214755, 2022). "Here, we sought to determine how GZB and GZK expression in NK-cells, and CD4+, CD8+, and gamma-delta T-cells, quantified in terms of positive cell frequency and mean fluorescence intensity (MFI), differed with age, age-related health-traits and the antibody response to high-dose influenza vaccine." (PMID 36685324, 2022). "Furthermore, using a newly developed DC specific ICAM-1 KO mouse, we found normal early Ag specific naïve CD4+ and CD8+ T cell priming by influenza expressed antigens, normal Ag stimulated CD8+ T cell binding to ICAM-1 deficient DCs and intact CD8+ lymphocyte differentiation." (PMID 36895258, 2022). "However, blocking TGFβ signaling in vivo, using either anti-TGFβ blocking antibody or the TGFβRII CD4+ T cell conditional-dominant negative (DN) mouse model (dnTGFβRII), did not alter the frequency of Tfh in models of NP-KLH immunization and influenza infection." (PMID 36072589, 2022).
influenza (continued). "Additionally, an increased frequency of KIR+CD8+ T cells, but not CD4+ Tregs, was observed in the peripheral blood of influenza-infected patients, which suggests that KIR+CD8+ T cells are generally induced as part of an infectious disease response." (PMID 35258337, 2022). "Despite the fact that adoptive transfer of CD4+ T-cells isolated from OVX836-immunized mice did not confer full protection against influenza infection in our vaccination model, it has been proposed that CD4+ T-cells guide the formation of TRM in the lung during influenza infection." (PMID 34177921, 2021). "One cluster corresponded to pre-existing influenza virus-specific cells that presumably persisted from previous vaccination(s) or infection(s), whereas the second cluster reflected CD4+ T cells responding to influenza vaccination but not the specific peptides used for stimulation." (PMID 34205932, 2021). "Intra cellular cytokine staining revealed that the majority of CD8 influenza specific T cells in the BAL secreted IFNγ and TNF (39.9%), followed by IFNγ only producers (35.7%) and 14.5% produced all three cytokines (IFNγ, TNF, and IL-2), while CD4 T cells produced mainly IFNγ (49.3%)." (PMID 33193445, 2020). "Although directly comparable studies are not available, Ki-67 expression by CD4+ T cells has been shown with influenza vaccination, suggesting that its absence might be particular to RSV infection." (PMID 31815739, 2020). "Therefore, understanding of influenza virus infection-mediated CD8+ and CD4+ T cell response and pathogenesis using these TCR Tg mouse models would lead to the development of more efficient therapeutics and vaccines for human influenza infection." (PMID 33353154, 2020). "This implies that it is a CD4+ T cell cluster that is responsive to influenza vaccination but may not be responsive to the specific peptides used for stimulation in our experiments." (PMID 33310880, 2020). "In an influenza vaccine test, the intranodal (i.n.)delivery of naked mRNA elicited potent CD4 and CD8 T cell immune responses in mice, and repeated i.n. injection with modified mRNA led to priming antigen-specific CD4 and CD8 T cells, whereas subcutaneous, i.d. administration did not." (PMID 30972078, 2019). "Memory CD4 T cells promote robust reduction of viral titer in SCID mice during the first week of otherwise lethal doses of influenza, but without contributions from other components of the adaptive immune system, such as virus-specific antibody or CD8 T cells, viral titers are not fully cleared." (PMID 30641955, 2019). "Our studies show that in human vaccine responses to influenza, the serum antibody responses to HA are correlated with the elicitation of CD4 T cells specific for HA peptide epitopes and not those from other viral proteins contained in the vaccine, such as NP (nucleoprotein)." (PMID 31694141, 2019). "Therefore, CXCR6 is highly expressed by lung memory T-lymphocytes, but is not required for the retention and function of CD4+ or CD8+ TRM following influenza infection." (PMID 30899256, 2019). "The previous results, suggesting that CD4 T cells of each specificity primed in the LN home to the lung after influenza infection, were unexpected because of the distinct types of APC in the lung that may have the potential to remodel the CD4 T cell repertoire." (PMID 29681900, 2018). "Furthermore, a T cell-inducing vaccine mouse model identified that depletion of memory CD4+ T cells but not the CD8+ T cell compartment removed heterologous protection from lethal influenza challenges." (PMID 29587436, 2018). "Influenza vaccination strategies may therefore be improved by targeting conserved regions of HA and NA antigens for presentation by MHC molecules to expand the CD4+ T cell repertoire." (PMID 29552008, 2018).